SIRT3 (sirtuin 3)
Diseases named in the same sentence as SIRT3 in open-access papers (continued):
Sharing a sentence is not in itself a finding about the gene and the disease.
tumor (continued). "In agreement with SIRT3 functioning as a tumor suppressor, SIRT3 was a favorable prognostic indicator for multiple cancer in our study, including KIRC, KIRP, LGG, LUAD, PAAD, UCEC, and UVM." (PMID 32158696, 2020). "In this study, we investigated if the tumor-suppressive effect of Sirt3 is mediated through the ERα signaling pathway in MCF-7 cells." (PMID 32244715, 2020). "Some studies have shown that the SIRT3 promoter can be activated by the stress transcription factor NF-κB, and this resulted in activation of the SIRT3 transcriptional in human tumor cells." (PMID 33062145, 2020). "In contrast, SIRT3 has been identified as a tumor suppressor in HCC, breast cancer, ovarian cancer, and leukemia." (PMID 32306906, 2020). "Our findings provide another piece of the puzzle in the holistic picture of cisplatin inducing tumor cell death by inhibiting SIRT3 regulated one-carbon metabolism." (PMID 32811824, 2020). "Results showed that SIRT1, 2, and 4 were up-regulated in tumor tissues while SIRT3 and 5 displayed decreased expression levels." (PMID 33093847, 2020). "Consistent with a role for SIRT3 and SIRT4 as tumor suppressor proteins, knock-out mouse lines for SIRT3 and SIRT4 develop mammary and lung tumors, respectively." (PMID 32846968, 2020). "SIRT3 regulates tumor progression by changing this excessive modification back to a normal condition." (PMID 32724473, 2020). "That is, PD-L1 promotes tumor growth and metastasis via ITGB4/SNAI1/SIRT3 signaling, and this is one of the main causes of PD-L1 resistance." (PMID 32000802, 2020). "In this situation, tumor cells increased SIRT3-driven mitophagy to counteract the damaging effects of oxygen reduction to a point that SIRT3 inhibition increased apoptotic cell death and ROS accumulation." (PMID 31210843, 2019). "Staining intensity was subsequently quantified using automated HistoQuest software that revealed that MnSOD-K68-Ac levels are significantly higher, and SIRT3 protein levels are markedly lower in the luminal B samples, as compared to luminal A tumor samples." (PMID 31160585, 2019). "On the one hand, SIRT3 functions as a tumor suppressor, decreasing tumorigenesis by suppressing glycolysis proliferation and its downstream transcriptional activity under hypoxic conditions." (PMID 31817470, 2019). "SIRT3 primarily serves as a tumor suppressor by limiting reactive oxygen species levels and antagonizing hypoxia-inducible factor 1-α, which fights against a metabolic switch to aerobic glycolysis." (PMID 31572453, 2019). "SIRT1 overexpression correlated with smaller tumor size, while SIRT3 under-expression correlated with larger tumor size." (PMID 31139150, 2019).
tumor (continued). "In the cases where non-cancerous adjacent liver tissue was present, we showed an absent/slight positivity of SIRT-3 and a negative expression of p-mTOR, suggesting that the presence of tumor strongly affected SIRT-3 and p-mTOR expression." (PMID 30917505, 2019). "The TMA was stained using anti-MnSOD-K68-Ac (see (b for antibody specificity) and anti-SIRT3 antibodies, and representative IHC images for luminal A and B tumor samples are shown." (PMID 31160585, 2019). "SIRT3 mainly appeared in the cytoplasm in tumor tissue, but they were at the same time appearing in the cytoplasm and nucleus of para-tumorous and non-tumorous tissues." (PMID 31076630, 2019). "Tumor suppression is associated with upregulation of SIRT1 levels, whereas SIRT3 and SIRT5 act differently as tumor promoters." (PMID 31137785, 2019). "CT exerted its anti‐tumor effect by targeting STAT3/SIRT3/HIF‐1α signaling pathway in vitro and in vivo." (PMID 30094960, 2018). "SIRT3 expression is an independent prognostic marker of survival to act as a tumor suppressor in GC." (PMID 27686535, 2017). "SIRT3 is likely to function as a mitochondrial tumor suppressor in GC to affect the progression of patients with GC by exerting direct control on HIF‐1a." (PMID 27686535, 2017). "SIRT3 acts as a tumor suppressor, at least in part via its ability to suppress reactive oxygen species (ROS) and regulate hypoxia inducible factor-1-alpha (HIF-1α)." (PMID 28197299, 2017). "It has been reported that SIRT3 expression level is inversely correlated with such factors as tumor infiltration, tumor differentiation, and tumor stage." (PMID 27686535, 2017). "To conclude, SIRT3 can function as a tumor suppressor by inhibiting the Warburg effect, which indicates its importance in therapeutic approaches." (PMID 27659520, 2017). "The secondary scoring method was used to evaluate the intensity of SIRT3 expression between tumor and adjacent tissue (0–2, low expression; 3–5, moderate expression; and 6-7, high expression)." (PMID 28947845, 2017). "Sirtuins (SIRTs) are nicotinamide adenine dinucleotide (NAD+)-dependent deacetylases and mitochondrial SIRT3 is known to be a tumor suppressor via its ability to suppress ROS and hypoxia inducible factor 1α (HIF-1α)." (PMID 29108235, 2017). "Recently, SIRT3 was reported to act as a mitochondrial localized tumor suppressor via its ability to inhibit mitochondrial ROS production." (PMID 29108235, 2017). "SIRT3 downregulation reduces tumor burden in vivo; however, significant decreases in SIRT3 mRNA and protein level were due to the effect of (‐)‐epigallocatechin‐3‐gallate, an antioxidative catechin commonly found in green tea." (PMID 27686535, 2017). "Tumor weights and volumes derived from SIRT3-overexpressing cells were smaller than those from the un-induced cells." (PMID 29108235, 2017). "CDK1 also stimulates the enzymatic activity of SIRT3, which enhances mitochondrial function and tumor radioresistance." (PMID 28434945, 2017). "We found that tumor volume derived from SIRT3 knockdown cells was significantly increased, compared with control cells." (PMID 29108235, 2017). "There are evidences that SIRT3 is involved in tumor development and progression by regulating cell apoptosis, genomic instability and mutation, cell proliferation and signal transduction, cell energy metabolism, development of inflammation, and tumor invasion." (PMID 28947845, 2017). "Depletion of Sirt3 augmented apoptosis in the tumor cells treated with hypoxia, as evidenced by an increase in Annexin V staining." (PMID 27270321, 2016).
tumor (continued). "Recent data suggest that SIRT3 acts as a tumor suppressor by inhibiting glycolysis metabolism after the deacetylation and activation of pyruvate dehydrogenase; thus, also the role of SIRT3 in cancer is debatable." (PMID 27226812, 2016). "In this study, we intended to determine the roles of Sirt3 in regulating autophagy and apoptosis in tumor cells undergoing stress." (PMID 27270321, 2016). "Silencing of Sirt3 expression markedly blunted autophagic response in the tumor cells subjected to hypoxia, as determined by a decrease in LC3-II and Atg5–12 complex, and an increase in p62 protein." (PMID 27270321, 2016). "The ability of SIRT3 to suppress tumor growth via inhibiting reactive oxygen species(ROS) production and regulating HIF-1α stabilization of host cells has attracted considerable attention in recent years." (PMID 27483432, 2016). "SIRT3 appears to be a tumor suppressor mainly through its ability to repress reactive oxygen species (ROS) and HIF-1α, which fights against metabolic switch towards aerobic glycolysis." (PMID 27916001, 2016). "We found that there was a co-localization of GFP-LC3 puncta with mitochondria (red) in tumor cells subjected to hypoxia, and inhibition of Sirt3 decreased the localization of LC3 on mitochondria." (PMID 27270321, 2016). "SIRT3 can regulate the enzymatic activity of MnSOD to maintain the balance of ROS, attributing its tumor-suppression effect." (PMID 27483432, 2016). "We showed that Sirt3 is important for the clearance of the damaged mitochondria through activating mitophagy, and silencing of Sirt3 expression can enhance the sensitivity of tumor cells to stress by inhibiting autophagy and promoting apoptosis." (PMID 27270321, 2016). "Overexpression of SIRT3 has been shown to inhibit tumor proliferation through the repression of glycolysis." (PMID 27559313, 2016). "Overexpression of Sirt3 in vivo was capable of attenuate tumorigenesis in xenografts, even after tumor initiation." (PMID 27023612, 2016). "Global loss of the Sirt3 gene augments mitochondrial ROS levels, reduces OCR, NAD+ levels, and ATP production, and promotes radiation-induced genotoxic stress response and a tumor permissive phenotype." (PMID 26370974, 2015). "Mechanistically, the tumor suppression effect of SIRT3 was achieved via its inhibition of the PI3K/Akt pathway." (PMID 26317998, 2015). "Patients presenting with low levels of cytoplasmic SIRT3 in their tumour had a significantly shorter time to recurrence than those with high levels of cytoplasmic SIRT3 (p = 0.05, mean recurrence time 11.8 vs 30.7 months)." (PMID 26121130, 2015). "The average weight of the tumors derived from SIRT3 overexpressing cells was 0.7079g, significantly bigger than the average tumor weight of control (NC), p = 0.015." (PMID 26121691, 2015). "Although exact mechanism causing SIRT3-mediated LDHA regulation needs to be further investigated, these results demonstrate that LDHA controlled glycolysis pathway that accelerates tumor bioenergetics can be affected by SIRT3 expression levels." (PMID 26121691, 2015). "It has been suggested that activation of SIRT3 causes a switch from glycolysis to oxidative phosphorylation and activation of the tricarboxylic acid (TCA) cycle, subsequently slowing down tumour cell growth." (PMID 26121130, 2015). "Although accumulating evidences indicates that SIRT3 plays a key role in protection of normal cells against aging and malignant transformation, its function in already transformed cells such as tumor cells that express SIRT3 needs to be investigated." (PMID 26121691, 2015). "Low level SIRT3 expression in the tumour cytoplasm correlated with more aggressive tumours, and a shorter time to relapse and death, in the absence of chemotherapeutic intervention." (PMID 26121130, 2015). "Collectively, all these results suggest that OA inhibits tumor growth through the regulation of SIRT3-mediated HIF1α destabilization." (PMID 25855962, 2015).
tumor (continued). "Among them, we selected SIRT3 for further investigation because it is a mitochondria-localized tumor suppressor required for the maintenance of mitochondrial integrity and metabolism." (PMID 25103363, 2014). "Peritumoral Sirt3 also showed prognostic role in groups when classified by the following variables: single tumor (OS, P = 0.023; TTR, P = 0.016), tumor differentiation grade I-II (OS, P = 0.028; TTR, P = 0.009)." (PMID 24774224, 2014). "Our study indicates that high SIRT3 expression in the cytoplasm significantly correlates with high tumor grades, positive lymph node status, and poor prognosis." (PMID 25105144, 2014). "Overall, current evidence suggests that, by maintaining low cellular ROS levels, SIRT3 inhibits glycolytic metabolism, and suppresses tumor development and progression." (PMID 25085992, 2014). "On univariate analysis, patients with lower expression of Sirt3 in tumor were prone to lower OS (P = 0.001) and shorter TTR (P = 0.011)." (PMID 24774224, 2014). "SIRT3 serves as a mitochondria-localized tumor suppressor and is required for integrity and metabolism of mitochondria during stress." (PMID 25105144, 2014). "It has been proposed that Sirt3 regulated mitochondrial acetylation and ROS generation, and therefore mediated the tumor-inhibiting role in cancer." (PMID 24774224, 2014). "Surprisingly, we found that the SIRT3 proteins from tumor and normal tissues of patients (OSCC_30, 31, 32, 39, 482) who carried c.622G > A had drastically lower levels of SIRT3 activity compared tissues from normal individuals." (PMID 23800187, 2013). "In our study, we determined the endogenous SIRT3 activity from 10 pairs of matched normal and tumor tissue samples obtained from OSCC patients." (PMID 23800187, 2013). "Our findings are consistent with previous work showing that SIRT3 functions as a tumor suppressor through regulation of ROS." (PMID 23800187, 2013). "As a result, the cutoff score for low SIRT3 expression is 2.50, which indicated that tumor were defined as one with low SIRT3 expression when the IHC score was not higher than 2.50." (PMID 23272146, 2012). "To date, data suggest SIRT3 exhibits dichotomous functions dependent on cell contexts: either as tumor promoter or as tumor suppressor." (PMID 23272146, 2012). "Several published papers demonstrated a tumor suppressor role for SIRT3 via the ability of SIRT3 to negatively regulate ROS (reactive oxygen species) and HIF1-α (hypoxia inducible factor-1 α)." (PMID 23230084, 2012). "Our data demonstrate that SIRT1 and SIRT3 coordinately regulate fatty acid synthesis in tumor cells." (PMID 22768255, 2012). "Altogether, our results suggest that in our experimental settings, SIRT3 inhibited tumor growth mainly through deacetylation of Skp2 oncoprotein." (PMID 23230084, 2012). "Recent studies have also shown that SIRT3 has seemingly dichotomous role as either tumor promoter or tumor suppressor in cancer biology." (PMID 23230084, 2012). "It is noteworthy that our data indicate that tumor cells with low levels of SIRT3 grow slower, produce smaller tumors, and have less tumor volume compared with controls." (PMID 21472714, 2011). "Specifically, the mean tumor volumes for the SIRT3 down-regulated group and the control group were 26.948 mm3 and 112.325 mm3, respectively (P ≤ .001)." (PMID 21472714, 2011). "In agreement with our in vitro data, our mouse model data indicated that the down-regulation of SIRT3 in OSCC cells significantly inhibited tumor growth in vivo." (PMID 21472714, 2011). "In an H1299 xenograft model, OA-OEt reduced tumor growth without overt body-weight loss and increased tumor SIRT3 and cleaved caspase-3 with consistent mitochondrial marker changes." (PMID 42212315, 2026). "Sirt3 has been reported to exert both tumor-promoting and tumor-suppressive effects in cancer." (PMID 41596235, 2026). "SIRT3 can suppress tumor growth by downregulating hypoxia-inducible factor 1α (HIF-1α)." (PMID 41154474, 2025).
tumor (continued). "In contrast, a stable knockdown of SIRT3 by shRNA significantly promoted tumor growth in vivo." (PMID 41391757, 2025). "It has hypothesized that these opposing functions reflect a dynamic interplay between SIRT3's modulation of metabolic plasticity and redox equilibrium, influenced by tumor type, developmental stage, and microenvironmental conditions." (PMID 40860195, 2025). "The results showed that SIRT3 overexpression significantly reduced the tumor growth." (PMID 41391757, 2025). "SIRT3 has been reported as a tumor suppressor in studies of various human cancers by triggering metabolic reprogramming that promotes tumorigenesis, of which EC is of particular interest to clinicians because it is the most common solid tumor and the leading cause of cancer death." (PMID 40252727, 2025). "SIRT3 plays different roles in various cancers and is specific to tumor type." (PMID 40421455, 2025). "Given that investigations into the effects of SIRT3-reguated histone Kla on tumors are limited, SIRT3's role in regulating tumor initiation and progression remains unclear." (PMID 40252727, 2025). "Clinically, SIRT3 inhibitors such as Suramin are already being explored for tumor treatment." (PMID 40672388, 2025). "SIRT3 counteracts this hyper-modification, thereby modulating tumor progression." (PMID 39944690, 2025). "To further investigate whether the suppressive effect of RCC1 knockdown on tumor cell proliferation was mediated by SIRT3, we performed a SIRT3 knockdown in the RCC1-knockdown PANC1 cells." (PMID 41391757, 2025). "Despite its role in DNA repair and resistance to radiation therapy, SIRT3 also exhibits both oncogenic and tumor-suppressive properties, suggesting complex dual functions that warrant further investigation to better understand its contributions to chemotherapy and radiotherapy resistance." (PMID 40710178, 2025). "The decreased expression of SIRT3 in EC suggests that SIRT3 has a tumor suppressive effect in ESCC." (PMID 40252727, 2025). "In conclusion, the level of SIRT3 measured in a given cancer type may depend not only on the type of cancer but also, in the same cancer, on the moment during tumor history at which the analysis is performed." (PMID 38931477, 2024). "However, depending on the genetic background, SIRT3 can either function as an oncogene or as a tumor suppressor gene in different tumors." (PMID 39501597, 2024). "Our analysis showed that SIRT3 expression was higher in GBM tumor tissues than in normal tissues." (PMID 38395990, 2024). "As a key mitochondrial deacetylase, the role of SIRT3 in tumor has attracted extensive attention." (PMID 38773972, 2024). "Similarly, SIRT3 and SIRT6 exhibit tumor-suppressive functions, with their low expression associated with tumor progression and poor survival, establishing their potential as reliable biomarkers." (PMID 39682281, 2024). "Thus, evaluating their pharmacological activity based on various roles of SIRT3 in tumors can help identify the most suitable type of tumor for treatment, offering potential for developing new cancer treatment drugs." (PMID 38773972, 2024). "For example, in cancers where SIRT3 suppresses tumor growth by undermining the Warburg effect or inducing apoptosis, SIRT3 agonists could be beneficial." (PMID 38773972, 2024). "SIRT3 acts as either an oncogene or tumor suppressor by regulating cell death and growth." (PMID 38395990, 2024). "Monitoring mitochondrial metabolites like lactate in the tumor microenvironment may offer insights into modulating SIRT3 for improved cancer treatment outcomes." (PMID 38773972, 2024). "Even though the effects of SIRT3 may be specific to the types of tumours, upregulation of both SIRT3 and SIRT4 is currently being pursued as a potential strategy to improve cancer treatment outcomes." (PMID 38369747, 2024). "Additionally, SIRT3 reported to has a dual role in cancer, acting as either a tumor suppressor or promoter by regulating ROS levels in tumor cells." (PMID 38698042, 2024).